MOG (myelin oligodendrocyte glycoprotein)
Diseases named in the same sentence as MOG in open-access papers (continued):
Sharing a sentence is not in itself a finding about the gene and the disease.
experimental autoimmune encephalomyelitis (continued). "The pathogenicity of antibodies against MOG and AQP4 was shown using variants of rat experimental autoimmune encephalomyelitis (EAE)." (PMID 37499337, 2023). "Whereas the role of MOG in the experimental autoimmune encephalomyelitis animal model is well-established, the pathogenesis of the human disease and the role of human MOG-IgG is still not fully clear." (PMID 36729854, 2023). "Experimental autoimmune encephalomyelitis (EAE) was induced with myelin oligodendrocyte glycoprotein (MOG35-55) in humanized TNFR1 knock-in mice." (PMID 37122019, 2023). "To test this possibility, we utilized the myelin oligodendrocyte glycoprotein (MOG)-induced experimental autoimmune encephalomyelitis (EAE) model of T cell-mediated autoimmune demyelinating neuroinflammation." (PMID 36746936, 2023). "In mice, treatment with E-WE thrombin reduced neuroinflammation and extracellular fibrin formation in myelin oligodendrocyte glycoprotein (MOG)-induced experimental autoimmune encephalomyelitis (EAE)." (PMID 37131631, 2023). "Experimental autoimmune encephalomyelitis (EAE) induced with a myelin oligodendrocyte glycoprotein (MOG) peptide is one of the most popular experimental models used for studying MS." (PMID 36902407, 2023). "In order to analyze the effects of transgenic HERV-W ENV expression in the context of neuroinflammation, we applied myelin oligodendrocyte glycoprotein fragment 33-55 peptide-induced experimental autoimmune encephalomyelitis (EAE)." (PMID 37695891, 2023). "To induce CNS autoimmunity, we used the mouse model of experimental autoimmune encephalomyelitis (EAE) induced by immunization with the myelin oligodendrocyte glycoprotein (MOG)-derived peptide (MOG35-55 peptide)." (PMID 37264394, 2023). "Myelin oligodendrocyte glycoprotein 35–55-induced experimental autoimmune encephalomyelitis MOG35–55 EAE is an MS mouse model in which the NLRP3 inflammasome plays a pivotal role in the pathogenesis of neuroinflammation." (PMID 38139284, 2023). "Next, we sought to evaluate the effect of MOG-Fc treatment on the development of autoimmune disease using experimental autoimmune encephalomyelitis (EAE)." (PMID 38057803, 2023). "We directly compared MOG35–55-induced experimental autoimmune encephalomyelitis exacerbated by MOG- and AQP4-IgG (versus isotype IgG, Iso-IgG)." (PMID 37499337, 2023). "For example, mouse immunization with myelin oligodendrocyte glycoprotein (MOG) is very efficient to induce the experimental autoimmune encephalomyelitis (EAE) with clinical and pathological similarities to multiple sclerosis (MS)." (PMID 36056452, 2022). "SJL/J and DBA/1 mice were immunized with the novel autoantigens or control antigens known to elicit a typical experimental autoimmune encephalomyelitis (EAE) disease course (PLP or MOG for SJL/J and DBA/1, respectively) together with adjuvants." (PMID 35476434, 2022). "Experimental autoimmune encephalomyelitis (EAE) is an autoimmune disease model of multiple sclerosis that can be induced in mice using the myelin oligodendrocyte glycoprotein (MOG) peptide." (PMID 35076460, 2022). "Murine experimental autoimmune encephalomyelitis (EAE) is an MS model generated by immunization of mice with myelin oligodendrocyte glycoprotein (MOG)." (PMID 35076022, 2022). "As a result, Atg7f/f CD4-Cre mice have a higher survival rate than normal control mice in a myelin oligodendrocyte glycoprotein (MOG)-induced experimental autoimmune encephalomyelitis (EAE) model." (PMID 35392563, 2022). "Here, we use a spontaneous model of experimental autoimmune encephalomyelitis (EAE) to study the clonality of the B cell response targeting myelin oligodendrocyte glycoprotein (MOG)." (PMID 35185870, 2022). "Previously we showed that TCDD inhibited myelin oligodendrocyte glycoprotein (MOG) peptide-specific IgG and attenuated disease in experimental autoimmune encephalomyelitis (EAE) model in mice." (PMID 35076460, 2022).
experimental autoimmune encephalomyelitis (continued). "Two studies have shown molecular mimicry with myelin oligodendrocyte glycoprotein, triggering an encephalitogenic T cell response in experimental autoimmune encephalomyelitis (EAE), an animal model for MS." (PMID 35645978, 2022). "IL-17A was reported to modulate the severity of myelin oligodendrocyte glycoprotein (MOG)-induced experimental autoimmune encephalomyelitis (EAE), although the magnitude of this effect varies substantially between studies." (PMID 36271145, 2022). "EPO exhibits neurotrophin-like properties, and axon protection is most effective when EPO is combined with high-dose methylprednisolone, as observed in a rat model of myelin oligodendrocyte glycoprotein (MOG)-induced experimental autoimmune encephalomyelitis." (PMID 35052875, 2022). "In the MOG-induced experimental autoimmune encephalomyelitis (EAE) mouse model of demyelination, we observed that catalpol significantly promoted OL development by enhancing the expression of glutathione S-transferase pi (GST-pi) in the affected brain." (PMID 36482934, 2022). "These cells can suppress myelin oligodendrocyte glycoprotein (MOG)–specific pathogenic CD4+ T cells through their cytolytic activity and thereby ameliorate experimental autoimmune encephalomyelitis (EAE)." (PMID 35258337, 2022). "We chose the myelin oligodendrocyte glycoprotein (MOG) experimental autoimmune encephalomyelitis model, in which tolerance to a myelin antigen is broken via immunization of adjuvanted MOG35-55 peptide." (PMID 35790728, 2022). "MOG35–55 is a low‐affinity T‐cell epitope derived from the self‐protein myelin oligodendrocyte glycoprotein that elicits experimental autoimmune encephalomyelitis (EAE) upon immunisation of mice." (PMID 34584693, 2021). "We also assessed the role of TRAIL on Tregs in two autoimmune mouse models: the NOD mouse model of autoimmune diabetes and the myelin oligodendrocyte glycoprotein (MOG) C57BL/6 model of experimental autoimmune encephalomyelitis." (PMID 33483333, 2021). "Accordingly, we aimed to elucidate the tolerogenic effects of MOG-PLGA particles on experimental autoimmune encephalomyelitis (EAE)." (PMID 34513625, 2021). "In a myelin oligodendrocyte glycoprotein (MOG)-induced experimental autoimmune encephalomyelitis (EAE) model, disease severity in Exo-cur mice was significantly reduced compared to vehicle and non-encapsulated curcumin-treated mice." (PMID 32712869, 2021). "Here, we investigated the roles of LPARs in myelin oligodendrocyte glycoprotein peptides-induced experimental autoimmune encephalomyelitis (EAE), an animal model of MS." (PMID 34666785, 2021). "Seldeg treatment of mice during antibody-mediated exacerbation of experimental autoimmune encephalomyelitis by patient-derived MOG-specific antibodies results in disease amelioration." (PMID 33212299, 2021). "For example, Tregs are critical for limiting multiple models of autoimmunity such as the NOD mouse, a spontaneous model of autoimmune diabetes, and the myelin oligodendrocyte glycoprotein (MOG) C57BL/6 model of experimental autoimmune encephalomyelitis (EAE)." (PMID 33483333, 2021). "PEA also reduced the expression of inflammatory cytokines in the myelin oligodendrocyte glycoprotein-induced experimental autoimmune encephalomyelitis (MOG-EAE) mice, an effect accompanied by decreased demyelination and axonal damage." (PMID 34681249, 2021). "The present study is based on yet unreported systematic profiling of transcriptional and phenotypic changes at the BBB during myelin oligodendrocyte glycoprotein (MOG)- induced experimental autoimmune encephalomyelitis (EAE), an animal model of MS." (PMID 33361796, 2020). "To investigate if increased MOG specific precursor frequencies in DO-KO mice correlated directly with autoimmune disease development, we tested the development of experimental autoimmune encephalomyelitis (EAE), a mouse model of multiple sclerosis (MS)." (PMID 32069316, 2020).
experimental autoimmune encephalomyelitis (continued). "HPK1-/- mice also possess an enhanced immunopathologic response to myelin oligodendrocyte glycoprotein (MOG) in a murine experimental autoimmune encephalomyelitis (EAE) model." (PMID 32896273, 2020). "Experimental autoimmune encephalomyelitis (EAE) induced with myelin oligodendrocyte glycoprotein (MOG) is an experimental model widely used for the study of MS." (PMID 33246492, 2020). "DCs targeted in vivo with an anti-DEC205 chimeric antibody to deliver myelin oligodendrocyte glycoprotein prevented subsequent experimental autoimmune encephalomyelitis." (PMID 32967687, 2020). "Encephalitogenic T cells from Myelin Oligodendrocyte Glycoprotein (MOG)-Induced Experimental Autoimmune Encephalomyelitis (EAE) mice showed significantly lower levels of TSPAN32 and increased levels of CD9, CD53, CD82 and CD151." (PMID 31487788, 2019). "Lack of Akt3 expression in mice results in a more severe clinical course during myelin-oligodendrocyte glycoprotein (MOG)-induced experimental autoimmune encephalomyelitis (EAE)." (PMID 31404142, 2019). "The mouse model of experimental autoimmune encephalomyelitis (EAE) based on active immunization with a fragment of myelin oligodendrocyte glycoprotein (MOG35-55) was used." (PMID 31221190, 2019). "We have also shown that transplantation of mESC-TEPs expressing self-antigen myelin oligodendrocyte glycoprotein (MOG) in mice results in immune tolerance to the MOG and the prevention of experimental autoimmune encephalomyelitis (EAE) development." (PMID 31387620, 2019). "One such outbreak occurred in a murine experimental autoimmune encephalomyelitis model generated via the administration of pertussis toxin and a myelin oligodendrocyte glycoprotein fragment." (PMID 30894434, 2019). "MOG is also the dominant antigen for demyelinating antibodies in experimental autoimmune encephalomyelitis (EAE), the predominant animal model of multiple sclerosis (MS), and MOG-IgG can augment demyelination by cell-mediated and humoral immune responses." (PMID 31345223, 2019). "Previously, we have established two distinct progressive multiple sclerosis (MS) models by induction of experimental autoimmune encephalomyelitis (EAE) with myelin oligodendrocyte glycoprotein (MOG) in two mouse strains." (PMID 30941144, 2019). "As cynomolgus macaques immunized with rhMOG, all develop an experimental autoimmune encephalomyelitis (EAE), we assessed relatedness between anti-MOG-Abs associated diseases in both species." (PMID 31785610, 2019). "A study in C57BL/6J mice highlighted the ability of a myelin oligodendrocyte glycoprotein MOG35–55 peptide from heat-killed MAP to induce experimental autoimmune encephalomyelitis (EAE), which is considered a model condition for MS studies." (PMID 31597322, 2019). "Experimental autoimmune encephalomyelitis (EAE) was induced in C57BL/6 mice by subcutaneous injection of myelin oligodendrocyte glycoprotein (MOG35–55) peptide in complete Freund’s adjuvant (CFA) followed by pertussis toxin." (PMID 29471880, 2018). "In this study, the antibodies raised against MOG were used in a panel of assays analyzing the experimental autoimmune encephalomyelitis via T-cell dependent immune response, as well as in the MHC-restricted immune response produced against BTN." (PMID 29401697, 2018). "In another study, CAR Tregs were engineered with specificity for myelin oligodendrocyte glycoprotein (MOG) to suppress experimental autoimmune encephalomyelitis (EAE), a model relating to multiple sclerosis in humans." (PMID 30369931, 2018). "The animal model of MS, experimental autoimmune encephalomyelitis (EAE), can be induced by active immunization of susceptible mouse strains with myelin components such as myelin basic protein and myelin oligodendrocyte glycoprotein (MOG)." (PMID 29545809, 2018). "T cell responses against myelin oligodendrocyte glycoprotein (MOG) in experimental autoimmune encephalomyelitis (EAE) animal models." (PMID 28533781, 2017).
experimental autoimmune encephalomyelitis (continued). "Injection of CTlo- or cAMP-DCs exerted MOG peptide-specific protective effects in experimental autoimmune encephalomyelitis (EAE) by inducing Foxp3+ Tregs and reducing Th17 responses." (PMID 28759565, 2017). "We examined the potential of hPSC therapy in preventing the onset or attenuating the course of established disease in a murine MS model of myelin oligodendrocyte glycoprotein‐induced experimental autoimmune encephalomyelitis." (PMID 28371563, 2017). "One of the most common and reliable animal models is experimental autoimmune encephalomyelitis (EAE) induced by active immunization of mice with the immunogenic peptide epitope MOG35–55 of myelin oligodendrocyte glycoprotein (MOG)." (PMID 29162133, 2017). "Immunization with myelin oligodendrocyte glycoprotein (MOG35-55) peptide induces the generation of autoreactive T cells that can trigger the onset of experimental autoimmune encephalomyelitis (EAE) in mice." (PMID 29163764, 2017). "Many of these insights stem from studies in animal models like myelin oligodendrocyte glycoprotein induced experimental autoimmune encephalomyelitis (MOG-EAE), which mimics many aspects of MS." (PMID 28273090, 2017). "Injection of a specific fragment of MOG is used to promote experimental autoimmune encephalomyelitis in mice in order to reproduce white matter lesions described in multiple sclerosis, suggesting that MOG can play a deleterious role in demyelinating diseases." (PMID 28910378, 2017). "It is noteworthy that adoptive transfer of myelin oligodendrocyte glycoprotein (MOG)-specific Th17 cells reproduces experimental autoimmune encephalomyelitis (EAE), an experimental model of MS." (PMID 28593439, 2017). "The clinical efficacy of sIL-23R was evaluated in myelin oligodendrocyte glycoprotein-induced experimental autoimmune encephalomyelitis mice intravenously injected with a single dose of adeno-associated virus AAV8–sIL-23R vectors." (PMID 28593439, 2017). "OCT and MRI can be used to reliably monitor neurodegeneration in experimental models of MS such as myelin oligodendrocyte glycoprotein (MOG) peptide induced experimental autoimmune encephalomyelitis (EAE), a common MS model in rodents." (PMID 27854301, 2016). "Myelin-oligodendrocyte-glycoprotein (MOG)-induced experimental autoimmune encephalomyelitis (EAE) is an animal model of multiple sclerosis (MS), a chronic autoimmune disease of the CNS that results in disability." (PMID 27519689, 2016). "In a model of myelin-oligodendrocyte glycoprotein–induced experimental autoimmune encephalomyelitis (EAE), Akt3-/- mice were more severely affected than wild-type mice." (PMID 27193124, 2016). "We have previously shown that induction of adaptive angioplasticity modulates the disease pattern in myelin oligodendrocyte glycoprotein (MOG)-induced experimental autoimmune encephalomyelitis (EAE)." (PMID 26785841, 2016). "We have shown that acclimatization to mild hypoxia ameliorates the signs and symptoms of myelin oligodendrocyte glycoprotein (MOG)-peptide-induced experimental autoimmune encephalomyelitis (EAE)." (PMID 26785841, 2016). "Myelin oligodendrocyte glycoprotein (MOG)-induced experimental autoimmune encephalomyelitis (EAE) is a widely used animal model for multiple sclerosis." (PMID 27903258, 2016). "In a myelin oligodendrocyte glycoprotein (MOG)-induced experimental autoimmune encephalomyelitis (EAE) rat model of MS, neuronal CX3CL1 was reported unchanged and remained at control levels." (PMID 27549131, 2016). "Correspondingly, treatment with anti-LINGO-1 antibody resulted in spinal cord remyelination and improved axonal integrity in MOG-induced experimental autoimmune encephalomyelitis and lysolecithin-induced focal spinal cord demyelination in rats." (PMID 26409478, 2016).
experimental autoimmune encephalomyelitis (continued). "Rather, in a model of experimental autoimmune encephalomyelitis (EAE) induced by myelin oligodendrocyte glycoprotein (MOG) exposure, splenocytes and lymphocytes from Mmp7-/- mice were able to respond to MOG and induce EAE in wild type mice." (PMID 26933888, 2016). "Following induction of experimental autoimmune encephalomyelitis (EAE) by direct immunization with myelin oligodendrocyte glycoprotein, mice were injected with anti-hnRNP A1 or control antibodies." (PMID 27391474, 2016). "Myelin-oligodendrocyte-glycoprotein (MOG)-induced experimental autoimmune encephalomyelitis (EAE) in rats reproduces major aspects of the human pathology." (PMID 27519689, 2016). "In murine myelin oligodendrocyte glycoprotein (MOG)-induced experimental autoimmune encephalomyelitis (EAE) ganciclovir strongly inhibited microglial proliferation, prevented T cell infiltration into the CNS, and strongly ameliorated disease severity in mice." (PMID 26447351, 2015). "Mice with genetic Sirt1 deletion specifically in dendritic cells (DCs) are resistant to myelin oligodendrocyte glycoprotein (MOG)-induced experimental autoimmune encephalomyelitis (EAE)." (PMID 26703582, 2015). "Myelin oligodendrocyte glycoprotein (MOG)-induced experimental autoimmune encephalomyelitis (EAE) in Brown Norway rats (BN-rats) is a well-established animal model, especially of the neurodegenerative aspects of MS." (PMID 26426258, 2015). "Passive transfer of MOG-IgG antibodies exacerbates CNS damage in experimental autoimmune encephalomyelitis rodent models in which cellular immunity is the predominant pathogenic mechanism." (PMID 24685353, 2014). "These mice, and littermate controls, were immunized with myelin oligodendrocyte glycoprotein peptide 35-55 (MOG peptide) to induce experimental autoimmune encephalomyelitis (EAE)." (PMID 24924222, 2014). "Experimental autoimmune encephalomyelitis (EAE) was induced by myelin oligodendrocyte glycoprotein (MOG35–55) immunization and spinal cord pathology was assessed by immunohistochemistry." (PMID 24727978, 2014). "We here sought to dissect the extent of parent-of-origin effects in the etiology of an experimental MS-like disease, myelin oligodendrocyte glycoprotein (MOG)-induced experimental autoimmune encephalomyelitis (EAE) in rodents." (PMID 24676147, 2014). "We previously carried out the intraperitoneal (i.p.)transfer of genetically modified ES-DCs to protect against myelin oligodendrocyte glycoprotein (MOG)-induced experimental autoimmune encephalomyelitis (EAE)." (PMID 25522369, 2014). "Experimental autoimmune encephalomyelitis (EAE) was induced by immunization with myelin oligodendrocyte glycoprotein (MOG 35–55) in C57BL/6 female mice." (PMID 24592383, 2014). "C57BL/6 mice younger than eight weeks were resistant to experimental autoimmune encephalomyelitis (EAE) following active immunization with myelin oligodendrocyte glycoprotein (MOG) peptide (p) 35–55." (PMID 23705890, 2013). "Treatment with mTGF-β1-EXO, even after disease onset, inhibited the development and progression of myelin oligodendrocyte glycoprotein (MOG) peptide-induced experimental autoimmune encephalomyelitis (EAE)." (PMID 26082317, 2013). "The immunomodulatory properties of FAE were also investigated in the rodent model of myelin oligodendrocyte glycoprotein (MOG) induced experimental autoimmune encephalomyelitis (MOG-EAE), an animal model that mimics several aspects of MS." (PMID 20668697, 2010). "In particular, myelin oligodendrocyte glycoprotein induced experimental autoimmune encephalomyelitis (MOG-EAE) mimics many features of relapsing-progressive or secondary progressive MS." (PMID 19865482, 2009). "Myelin oligodendrocyte glycoprotein (MOG)-induced experimental autoimmune encephalomyelitis (EAE) is an animal model of MS with similarities in pathogenicity and histopathology." (PMID 19915720, 2009).